POTEH (POTE ankyrin domain family member H)
Synonyms: A26C3; ACTBL1; POTE22; CT104.7
Tractability: PROTAC: ubiquitination databases record sites on it.
Gene: Protein-coding gene on chromosome 22 (15,690,026 to 15,721,631, forward strand). Ensembl gene ENSG00000198062.
Genetic constraint (gnomAD): Loss-of-function variants: 6 observed, 21.48 expected, observed/expected ratio (o/e) 0.28, 90% interval 0.15 to 0.55. The synonymous counts are far from expectation, so gnomAD's model fits this gene poorly and the ratio says little. Missense variants: 114 observed, 268.41 expected, observed/expected ratio (o/e) 0.42, 90% interval 0.36 to 0.5. Synonymous variants: 37 observed, 84.7 expected, observed/expected ratio (o/e) 0.44, 90% interval 0.34 to 0.57.
Homologues: Paralogues in human: POTEM (92% identical), POTEG (92% identical), POTEI (85% identical), POTEF (84% identical), POTEE (84% identical), POTEB3 (83% identical), POTEC (81% identical), POTED (81% identical), POTEJ (78% identical), POTEB (77% identical), POTEB2 (77% identical), POTEA (52% identical), and 2 more.
Diseases named in the same sentence as POTEH in open-access papers:
POTEH is named in the same sentence as 4 diseases in open-access papers, as found by Europe PMC text mining. Sharing a sentence is not in itself a finding about the gene and the disease. The quoted sentences say what the papers report.
astrocytomas (1 paper, 2016). "Our data have verified four new hypomethylated genes, F10, POTEH, LMO3 and CPEB1, and their prognostic values in astrocytomas." (PMID 26701852, 2016).
glioma (1 paper, 2014). A benign or malignant brain and spinal cord tumor that arises from glial cells (astrocytes, oligodendrocytes, ependymal cells). "Recently, hypomethylation of POTEH has been proposed as a new epigenetic biomarker for glioma prognosis." (PMID 24818602, 2014).
cancer (1 paper, 2015). A tumor composed of atypical neoplastic, often pleomorphic cells that invade other tissues. "They found that POTE proteins correlated well with malignant progression and metastasis in a variety of tissues and that POTEG and /or POTEH are pivotal for cancer cells to grow and survive." (PMID 25860145, 2015).
POTEH also shares sentences with these, for which no sentence is quoted: tumor (1 paper).